BRAF (B-Raf proto-oncogene, serine/threonine kinase)
Diseases named in the same sentence as BRAF in open-access papers (continued):
Sharing a sentence is not in itself a finding about the gene and the disease.
non-small cell lung carcinoma (continued). "Non-small cell Lung cancer is now a heterogenous disease with EGFR, BRAF, Her2/Neu aberrations or ALK, ROS1, RET or FGFR fusions." (PMID 26510912, 2015). "The main druggable genetic alterations in non-small cell lung cancer involved EGFR (epidermal growth factor receptor), KRAS (Kirsten rat sarcoma viral oncogene homolog), ALK (anaplastic lymphoma kinase), BRAF (V-raf murine sarcoma oncogene homolog B1), and ROS1 (c-ros oncogene 1) genes." (PMID 39199653, 2024). "In non-small cell lung cancer (NSCLC), BRAF mutations commonly occur in never-smokers, women, and aggressive histological types and accounts for 1%–2% of adenocarcinoma." (PMID 35433454, 2022). "Additionally, TINCR can interact with ATP-Citrate Lyase (ACLY), BRAF, and Staphylococcal Nuclease and Tudor Domain Containing 1 (SND1) in nasopharyngeal cancer, non-small cell lung cancer, and post-burn skin fibroblasts, respectively." (PMID 34057016, 2021). "For instance, in non-small cell lung cancer patients with no available tumor biopsy, blood is the only source for detecting genetic alterations, including EGFR, KRAS, BRAF, PIK3CA mutations, and ALK rearrangements." (PMID 34359285, 2021). "Activation of ALK/STAT3 in T cell lymphoma, AP-1/JAK/STAT in classical Hodgkin lymphoma (cHL), the microRNA-200/ZEB1 axis in non-small-cell lung cancer (NSCLC), c-jun/STAT3 in BRAF inhibitor-resistant melanoma, and PI3K in glioma have each been reported to upregulate PD-L1 expression on tumor cells." (PMID 31730010, 2019). "The purpose of this study was to test genetic biomarkers used in clinical practice (EGFR, ALK) and candidate biomarkers identified by the French National Cancer Institute (KRAS, BRAF, PIK3CA, HER2) in patients with metastatic non-small-cell lung cancer for whom two tumor samples were available." (PMID 26968843, 2016). "RET kinase domain fusion with kinesin family member 5B was identified in about 1–2% of patients with non-small-cell lung cancer (NSCLC), who were negative for mutations or rearrangements in other common oncogenic drivers such as EGFR, HER, ERBB2, BRAF, KRAS, ALK, etc.." (PMID 32993133, 2020). "Trametinib as MEK inhibitor and Dabrafenib as serine-threonine kinase (BRAF) inhibitor are the chemotherapeutics that can be used in non-small cell lung carcinoma (NSCLC)." (PMID 37046057, 2023). "In conclusion, the genetic mutations associated with PACC are different from those implicated in non-small cell lung cancer, and EGFR, KRAS, BRAF, ALK, PIK3CA, PDGFRA, and DDR2 may not be driver genes in PACC; we must identify other genes for targeted therapy against PACC." (PMID 26373952, 2015).
metastatic colorectal cancer (279 papers, 2009 to 2026). "The activating BRAF mutation V600E occurs in 8%-12% of metastatic colorectal cancers (mCRC) and is associated with peritoneal carcinomatosis (PC) and poor prognosis." (PMID 41920914, 2026). "The serine-threonine protein kinase B-RAF (BRAF) V600 mutation confers a poor prognosis in metastatic colorectal cancer (mCRC)." (PMID 42127914, 2026). "Encorafenib plus cetuximab was previously established as a SOC therapy for BRAF-mutated metastatic colorectal cancer with an OS benefit." (PMID 41056448, 2025). "Roughly 10% of metastatic colorectal cancers (mCRCs) harbor the BRAF V600E mutation, a molecular alteration strongly associated with resistance to conventional chemotherapy and a generally poor prognosis." (PMID 40332392, 2025). "It does appear from this study that, for patients who have metastatic colorectal cancer bearing BRAF V600E mutations, the new SOC first-line therapy should be encorafenib-cetuximab-mFOLFOX6." (PMID 41056448, 2025). "BRAF V600E mutations are found in around 10 % of patients with metastatic colorectal cancer, being an indicator of poor prognosis." (PMID 40977811, 2025). "Despite advances in systemic therapeutic approaches, metastatic colorectal cancer (mCRC) patients harboring BRAF or RAS mutations have poor outcomes." (PMID 40750758, 2025). "VCC regimen exhibited manageable adverse reactions and efficacy in BRAF V600E-mutated/MSS patients with metastatic colorectal cancer who progressed after standard treatment." (PMID 41225509, 2025). "Patients with BRAF V600E-mutated/microsatellite stable (MSS) metastatic colorectal cancer (mCRC) are associated with a poor prognosis." (PMID 41225509, 2025). "A combination of vemurafenib, cetuximab combined with camrelizumab exhibited manageable adverse reactions and efficacy in BRAF V600E-mutated/MSS patients with metastatic colorectal cancer who progressed after standard treatment." (PMID 41225509, 2025). "BRAF activating mutations occur in approximately 10% of metastatic colorectal cancer (CRCs) and are associated with worse prognosis in part due to an inferior response to standard chemotherapy." (PMID 40264166, 2025). "Background/Objective: The prognostic value of specific hot-spot mutations within KRAS, NRAS, and BRAF genes in metastatic colorectal cancer (mCRC) genes remains debatable." (PMID 40075837, 2025). "BRAF activating mutations occur in approximately 10% of metastatic colorectal cancers (CRCs) and are associated with poor prognosis in part due to an inferior response to high-dose 5-Flurouracil-based chemotherapy." (PMID 40264166, 2025). "Despite advances in the treatment of metastatic colorectal cancer (mCRC), there remains an unmet need for effective therapies, particularly for patients with BRAF- or RAS-mutated tumors associated with poor prognosis." (PMID 40750758, 2025). "Beyond treatment efficacy, multiple clinical and molecular characteristics have been implicated as prognostic factors in BRAF V600E-mutant metastatic colorectal cancer (mCRC)." (PMID 40761242, 2025). "BRAF V600E-mutant metastatic colorectal cancer (mCRC) is associated with poor prognosis and limited response to standard therapies." (PMID 40761242, 2025). "The prognostic significance of KRAS and BRAF mutations is well-established in metastatic colorectal cancer (CRC) but remains uncertain in early-stage tumors." (PMID 40279317, 2025). "Mutations in KRAS at codon 12 or 13 (observed in 35% to 45% of cases) or the v-raf murine sarcoma viral oncogene homolog B (BRAF) V600E mutation (approximately 10%) confer resistance to cetuximab-based therapies in metastatic colorectal cancer (mCRC)." (PMID 40565003, 2025). "Although V600E accounts for the majority of the BRAF mutations in metastatic colorectal cancer (mCRC), non-V600 BRAF variants have been shown in recent years to represent a distinct molecular subtype." (PMID 38398128, 2024).
metastatic colorectal cancer (continued). "Mutations involving RAS and BRAF hold prognostic and predictive significance in metastatic colorectal cancer." (PMID 39682117, 2024). "BRAF-V600E mutated metastatic colorectal cancer (mCRC) (BRAF-V600E mCRC) impacts patients globally; Latin America (LA) has a 4%–12% prevalence." (PMID 40171464, 2024). "Microsatellite-stable BRAF-mutated metastatic colorectal cancer patients treated with anti-EGFR/BRAF combinations had better responses and survival outcomes when RNF43 was mutated compared with wild-type cases." (PMID 39452477, 2024). "In the case of patients with metastatic colorectal cancer (mCRC), BRAF mutations are detected in roughly 5–10%." (PMID 39073010, 2024). "Recent studies have shown the efficacy of ddPCR in detecting RAS and BRAF mutations in metastatic colorectal cancer (mCRC)." (PMID 39064004, 2024). "Mutations in RAS and BRAF genes are widely recognized as the primary drivers of resistance to anti-EGFR agents in metastatic colorectal cancer (mCRC)." (PMID 39064004, 2024). "While the predictive and prognostic significance of KRAS and BRAF mutations in metastatic colorectal cancer (mCRC) is well established, their impact on localized colorectal cancer (CRC) remains not fully elucidated." (PMID 39682117, 2024). "Patients with atypical (nonV600) BRAF mutations represent a unique category of metastatic colorectal cancer patients." (PMID 38398128, 2024). "The objective of this study was to evaluate the predictive value of 18F-fluorodeoxyglucose [18F]FDG positron emission tomography (PET-CT) radiomic parameters in relation to KRAS/BRAF/EGFR mutations in patients with metastatic colorectal cancer (mCRC)." (PMID 39722096, 2024). "The combination of encorafenib with cetuximab has become the standard of care in patients with BRAF V600E-mutated metastatic colorectal cancer (mCRC) after a prior systemic therapy." (PMID 39255538, 2024). "BRAF mutations, particularly the V600E mutation, in metastatic colorectal cancer are associated with a poor prognosis and reduced response, especially when treated with EGFR inhibitors." (PMID 37686423, 2023). "Genotyping of tumor tissues to assess RAS and BRAF V600E mutations enables us to select optimal molecularly targeted therapies when considering treatment strategies for patients with metastatic colorectal cancer." (PMID 36900264, 2023). "On 8 April 2020, the FDA approved encorafenib in combination with cetuximab for metastatic colorectal cancer patients with a BRAF V600E mutation." (PMID 37686423, 2023). "Metastatic colorectal cancer (mCRC) with mutated BRAF exhibits distinct biological and molecular features that set it apart from other subtypes of CRC." (PMID 37958416, 2023). "The aim of this study was to describe survival outcomes and treatment patterns of metastatic colorectal cancer (mCRC) patients by v-raf murine sarcoma viral oncogene homolog B1 (BRAF) mutation status." (PMID 38136294, 2023). "This study focused on metastatic colorectal cancer (mCRC) and its correlation with a specific genetic mutation known as v-raf murine sarcoma viral oncogene homolog B1 (BRAF)." (PMID 38136294, 2023). "Despite the promising results shown by BRAFi treatments in combination with other MAPK pathway inhibitors (EGFRi or MEKi) in BRAF-mutated metastatic colorectal cancer (mCRC), the emergence of resistance mechanisms to these drugs limits their clinical benefit." (PMID 37958416, 2023). "This phase Ib dose-escalation study evaluated the maximum tolerated dose of WNT974 in combination with encorafenib and cetuximab in patients with BRAF V600E-mutant metastatic colorectal cancer with RNF43 mutations or RSPO fusions." (PMID 36811382, 2023). "This study aimed to validate BRAFV600E/RNF43 co-mutations as predictive biomarkers of benefit to anti-EGFR/BRAF therapy, using clinical data from the Flatiron Health-Foundation Medicine real-world clinico-genomic metastatic colorectal cancer database." (PMID 36779536, 2023).
metastatic colorectal cancer (continued). "BRAF mutations in metastatic colorectal cancer are more frequently observed in older individuals (>70 years), current or former smokers, white patients, females, and those with KRAS wild-type tumors." (PMID 37686423, 2023). "In metastatic colorectal cancers, patients with BRAF V600E mutation had a shorter OS than BRAF V600E wild type." (PMID 35186740, 2022). "A BRAF inhibitor is currently approved in combination with the anti-EGFR monoclonal antibody cetuximab for second line treatment of metastatic colorectal cancers with BRAF mutations." (PMID 36079062, 2022). "The BEACON study confirms that encorafenib plus cetuximab has significant advantages in objective response rate and OS in BRAF V600E-mutated metastatic colorectal cancer In addition, studies combining encorafenib, cetuximab, and chemotherapy are also underway." (PMID 36339570, 2022). "Patients with BRAF V600E-mutated metastatic colorectal cancer are poorly responsive to chemotherapy and have an extremely poor prognosis with a median survival of only 12 months." (PMID 36339570, 2022). "BRAF mutations are used as biomarkers of therapy guidance in metastatic colorectal cancer based on the results of the phase III randomized BEACON trial." (PMID 36079062, 2022). "BRAF mutation in the metastatic colorectal cancer showed poor chemotherapeutic response and shorter the survival rate for patients." (PMID 36267655, 2022). "For example, immune checkpoint inhibitors (ICIs) have been approved only for patients with microsatellite instability, whereas dual anti-BRAF and anti-EGFR combinations are only available for metastatic colorectal cancers with the BRAF V600E mutation." (PMID 36497365, 2022). "This trial established that the combination of the BRAF inhibitor encorafenib with EGFR monoclonal antibody cetuximab was superior to chemotherapy in pretreated patients with metastatic colorectal cancer bearing BRAF V600E mutations." (PMID 36079062, 2022). "BRAF V600E is the most common potentially targetable mutation in metastatic colorectal cancer; however, RAF inhibitors have limited efficacy as single agents in treating patients with this alteration." (PMID 35267469, 2022). "The assessment of RAS and BRAF mutational status is one of the main steps in the diagnostic and therapeutic algorithm of metastatic colorectal cancer (mCRC)." (PMID 35463316, 2022). "The NIVACOR trial is a phase II study assessing the efficacy and safety of nivolumab in combination with FOLFOXIRI/bevacizumab in first-line setting in patients affected by metastatic colorectal cancer (mCRC) RAS/BRAF mutated." (PMID 34970487, 2021). "Backgroundand objectives: Patients with BRAF-mutated metastatic colorectal cancer have considerably poorer responses to conventional systemic treatment." (PMID 34946284, 2021). "Whereas, in metastatic colorectal cancer, BRAF mutation seems to have the poorest prognosis compared with KRAS and NRAS." (PMID 34063325, 2021). "The ESMO (2014), NICE (2020), and Australian (2017) guidelines recommend testing for BRAF mutation in metastatic colorectal cancer for prognostication and determination of response to anti-EGFR therapies." (PMID 34940086, 2021). "About 5%–12% of patients with metastatic colorectal cancer have the BRAF V600E mutation, which indicates poor prognosis or rapid disease progression." (PMID 34567559, 2021). "In metastatic colorectal cancer (mCRC), BRAF mutation represents a poor prognostic factor and median survival." (PMID 34073365, 2021).
metastatic colorectal cancer (continued). "Materials and Methods: This single-center case series included patients with BRAF-mutated metastatic colorectal cancer undergoing triplet therapy after failure of prior systemic treatment from 2016 to 2020." (PMID 34946284, 2021). "In a subgroup analysis of the TRIBE study, patients with metastatic colorectal cancer with the BRAF mutation were treated with FOLFOXIRI + bevacizumab (n = 16) and FOLFIRI + bevacizumab (n = 12)." (PMID 34567559, 2021). "BRAF mutations constitute an important poor prognostic factor in metastatic colorectal cancer (mCRC) and the development of treatments in this context is of great necessity to prolong patient survival." (PMID 33842313, 2021). "Somatic BRAF mutations occur in approximately 10% of metastatic colorectal cancers (mCRCs) and, according to the involved codon, are classified as V600E and in non-V600, accounting for 80% and 20%, respectively." (PMID 33925278, 2021). "The BRAF mutation occurs in about less than 10% of metastatic colorectal cancers and confers a poor prognosis." (PMID 34132476, 2021). "Recently, retrospective analysis began to shed light on metastatic colorectal cancers (mCRCs) harboring rare BRAF non-V600 mutations, documenting a distinct phenotype and a favorable prognosis." (PMID 33925278, 2021). "We evaluated the ability of the fully-automated molecular diagnostics platform Idylla for the detection of KRAS, NRAS and BRAF hotspot mutations in plasma from patients with metastatic colorectal cancer (mCRC)." (PMID 31940389, 2020). "Targeting BRAF signalling has recently been confirmed as a viable option for metastatic colorectal cancer cases with BRAF mutations." (PMID 33274713, 2020). "Mutations in KRAS, NRAS, and BRAF (RAS/BRAF) genes are the main predictive biomarkers for the response to anti-EGFR monoclonal antibodies (MAbs) targeted therapy in metastatic colorectal cancer (mCRC)." (PMID 32628708, 2020). "KRAS and BRAF mutations are prognostic and predictive tools in metastatic colorectal cancer, but little is known about their prognostic value in patients scheduled for cytoreductive surgery (CRS) and hyperthermic intraperitoneal chemotherapy (HIPEC)." (PMID 31571052, 2020). "The Raf murine sarcoma viral oncogene homolog B (BRAF) mutation is detected in 8–12% of metastatic colorectal cancers (mCRCs) and is strongly correlated with poor prognosis." (PMID 33152998, 2020). "BRAF box is now open and BRAF V600 mutations are now among targetable genomic alterations in metastatic colorectal cancer patients." (PMID 32670606, 2020). "Assessment of KRAS, NRAS (RAS) and BRAF mutations is a standard in the management of patients with metastatic colorectal cancer (mCRC)." (PMID 31265477, 2019). "The most common mutations in KRAS, NRAS and BRAF genes were detected in less than 90 minutes in tissue biopsies and plasma samples of metastatic colorectal cancer patients." (PMID 30562355, 2018). "A phase I/II trial evaluating WNT974 in combination with LGX818, a specific BRAF inhibitor, and cetuximab in patients with metastatic colorectal cancer bearing WNT and BRAF mutations is ongoing (NCT02278133)." (PMID 28476164, 2017). "So far, among molecular markers studied, MSI status and RAS, BRAF mutations represent important predictive factors of response to target agents in metastatic colorectal cancer." (PMID 28402263, 2017). "BRAF mutations are anticipated to have prognostic impact in metastatic colorectal cancer 20, 21, but their importance in localized disease is dubious." (PMID 28378527, 2017). "BRAF mutations occur in 8–10% of metastatic colorectal cancers but are reported in 10–22% of localized colon tumors." (PMID 28378527, 2017). "As predictive markers for anti-EGFR therapy, KRAS and BRAF mutations are routinely detected in primary and metastatic colorectal cancer (CRC) cells, but seldom in circulating tumor cells (CTCs)." (PMID 29100436, 2017).